MOG (myelin oligodendrocyte glycoprotein)
Diseases named in the same sentence as MOG in open-access papers (continued):
Sharing a sentence is not in itself a finding about the gene and the disease.
optic neuritis (continued). "Our study demonstrated longitudinal changes in the implicit times of various components of pVEPs and alterations in the thickness of the pRNFL as observed in OCT images of a 5-year-old girl with anti-MOG antibody-positive optic neuritis." (PMID 39184699, 2024). "At 4 years of age, she was also diagnosed with optic neuritis, including the presence of myelin oligodendrocyte glycoprotein (MOG) antibodies." (PMID 38236406, 2024). "In contrast, MOGAD showcases rapid-onset unilateral or bilateral vision loss akin to NMOSD, but it is characterized by antibodies against MOG, often resulting in favorable visual recovery, occasionally involving bilateral optic neuritis episodes." (PMID 39675357, 2024). "In this study, we utilized Weighted Gene Co-expression Network Analysis (WGCNA) to investigate the transcriptomic profiles of peripheral blood samples from patients with AQP4-ON and MOG-positive optic neuritis (MOG-ON), compared to healthy controls." (PMID 39238786, 2024). "We report our findings in a 5-year-old Japanese girl with unilateral optic neuritis who was seropositive for anti-myelin-oligodendrocyte glycoprotein (MOG) antibody." (PMID 39184699, 2024). "We have presented the longitudinal changes in the implicit times of pVEPs and the thickness of the pRNFL in a 5-year-old Japanese girl with unilateral optic neuritis who tested positive for anti-MOG antibodies over a period of 3.5 years." (PMID 39184699, 2024). "Because anti-MOG antibodies seropositive optic neuritis is a relatively new nosological entity, there are only a limited number of studies that investigated the changes in the retinal morphology and the VEPs in children." (PMID 39184699, 2024). "Several IMIDs linked to ON, such as aquaporin-4 antibody-associated optic neuritis (AQP4-ON), myelin oligodendrocyte glycoprotein antibody-associated optic neuritis (MOG-ON), and neuro-sarcoidosis, show remarkable response to corticosteroid treatment." (PMID 38867071, 2024). "Anti-MOG optic neuritis is highly steroid-responsive, with rapid improvement in symptoms after intravenous methyprednisone." (PMID 39598329, 2024). "MRI is the imaging modality of choice to confirm the presence of optic neuritis and displays characteristic features in MOG-ON that can help distinguish it from other aetiologies." (PMID 38783085, 2024). "The severe thinning is consistent with earlier reports in eyes with anti-MOG antibodies seropositive optic neuritis." (PMID 39184699, 2024). "With the progress of molecular biology and bioinformatics, current understandings of AQP4-related and MOG-related optic neuritis have transcended the realm of autoantibody discovery, advancing into the molecular mechanisms and the realm of epigenetics." (PMID 39238786, 2024). "In children, the most common presenting symptom is acute disseminated encephalomyelitis (36%), whereas the most common presentation for anti-MOG syndromes in adults is optic neuritis (88%)." (PMID 39598329, 2024). "Myelin oligodendrocyte glycoprotein antibody-associated disease (MOGAD) represents a spectrum of autoimmune disorders involving the central nervous system, including optic neuritis." (PMID 38903369, 2024). "In this study, we applied Weighted Gene Co-expression Network Analysis (WGCNA) to an in-depth transcriptomic analysis of peripheral blood samples from patients with AQP4 antibody and MOG antibody-positive optic neuritis." (PMID 39238786, 2024). "Our findings documented the course of the function and structures of an eye with anti-MOG antibody-positive optic neuritis." (PMID 39184699, 2024). "In contrast, MOG antibody-related optic neuritis is typically localized to the anterior part of the optic nerve and exhibits more pronounced inflammation compared to AQP4-IgG-positive cases." (PMID 39618752, 2024). "This study described an unusual instance of overlapping syndrome, characterized by the simultaneous occurrence of MOG and mGluR5 antibodies manifested as optic neuritis." (PMID 39151524, 2024).
optic neuritis (continued). "Unlike in MS, bilateral optic neuritis is common, with one study finding 42% of anti-MOG syndromes had bilateral optic neuritis and 31% had unilateral optic neuritis." (PMID 39598329, 2024). "Diagnostic criteria essentially depend on (i) the presence of IgG antibodies targeting MOG with (ii) characteristic neurological symptoms (including optic neuritis, myelitis, brainstem encephalitis, and encephalitis) resulting from (iii) demyelination." (PMID 36472724, 2024). "Based on the presence of MOG-IgG, the typical clinical characteristics of optic neuritis, and MRI scans showing features common to patients with MOGAD, the diagnosis of MOGAD was definitive." (PMID 39569189, 2024). "MOG antibodies have been isolated in other pediatric demyelinating conditions like optic neuritis, transverse myelitis and ADEM." (PMID 37841344, 2023). "Several studies have identified two MOG epitopes that exhibit strong affinity with human anti-MOG autoantibodies, particularly those isolated from patients with the optic neuritis phenotype." (PMID 37686172, 2023). "Herein, we introduce a rare case of anti-myelin oligodendrocyte glycoprotein (anti-MOG) antibody-positive optic neuritis developed shortly after AZ vaccination in a recipient of allogeneic HSCT with underlying chronic GVHD (cGVHD)." (PMID 37409268, 2023). "These also include anti-myelin oligodendrocyte glycoprotein (MOG) antibodies, which occur in other demyelinating diseases such as optic neuritis (ON), transverse myelitis or acute disseminated encephalomyelitis (ADEM)." (PMID 37638199, 2023). "Several studies have highlighted differences between anti-AQP4 antibody and anti-MOG antibody-positive optic neuritis." (PMID 37104301, 2023). "What is the difference between MOG-IgG-related optic neuritis, transverse myelitis, and tumefactive lesions in ADEM?" (PMID 36925938, 2023). "High titers of autoantibodies targeting MOG are identified in various demyelinating diseases, including optic neuritis, transverse myelitis, acute disseminated encephalomyelitis (ADEM), and cerebral cortical encephalitis." (PMID 36925938, 2023). "Among them, the spectrum of anti-MOG positive diseases, defined as anti-MOG antibody associated disease (MOGAD), is distinguished, which can manifest as optic neuritis, myelitis, or various forms of encephalitis (MOGAE)." (PMID 37638199, 2023). "The diagnosis of optic neuritis was well-confirmed by the presence of an anti-myelin oligodendrocyte glycoprotein antibody and the typical features of MRI image and Ophthalmoscopy." (PMID 37409268, 2023). "In anti-AQP4 seronegative patients, anti-myelin oligodendrocyte glycoprotein (MOG) has been detected in patients with optic neuritis and longitudinally extensive transverse myelitis." (PMID 37346048, 2023). "It has also been shown in MOG-positive optic neuritis or myelitis to have a higher recurrence rate when the brainstem is involved." (PMID 35356456, 2022). "The patient did well until he developed optic neuritis nearly 2 years later, and subsequent testing of stored serum from the time of his initial encephalitic presentation revealed positivity for anti-MOG." (PMID 36341089, 2022). "Myelin oligodendrocyte glycoprotein (MOG) antibodies have been identified in central nervous system inflammatory demyelinating disorders (MOG antibody disease), inclusive of optic neuritis, transverse myelitis, or acute disseminated encephalomyelitis." (PMID 36601183, 2022). "We believe this is the first study that evaluated the plasma LCN2 levels and their correlation with MOG-IgG titers in patients with optic neuritis." (PMID 35566760, 2022). "As an example, the disease associated with MOG-IgG (i.e., MOGAD) can manifest with different clinical-MRI phenotypes, such as optic neuritis, myelitis, encephalitis, ADEM, NMOSD, or combinations thereof." (PMID 35785363, 2022). "The correlation between plasma LCN2 levels and MOG-IgG titers in patients with optic neuritis was analyzed." (PMID 35566760, 2022).
optic neuritis (continued). "Patients with MOG-IgG–positive optic neuritis had significantly higher mean plasma LCN2 levels than controls and patients with MOG-IgG–negative optic neuritis (50.96, 30.86, and 37.60 ng/mL, respectively, p = 0.037)." (PMID 35566760, 2022). "Receiver operating characteristic (ROC) curves were constructed to assess and compare the ability of plasma LCN2 and MOG-IgG levels for predicting optic neuritis recurrence." (PMID 35566760, 2022). "In this study, the aim is to compare the recovery pattern among patients with acute myelin oligodendrocyte glycoprotein antibody-seropositive optic neuritis (MOG-Ab + ON) attacks and aquaporin-4 antibody-seropositive ON (AQP4-Ab + ON) or -seronegative ON." (PMID 35360549, 2022). "The patient 16 presented with optic neuritis in the right eye with MOG antibodies positive in serum 26 months after discharge." (PMID 36532000, 2022). "It is common to find increased autoimmune B cells against MOG-ab in CSF of patients with optic neuritis and patients with SLE." (PMID 35770018, 2022). "For example, when optic neuritis occurs in the setting of MOG-AD, it is typical to find extensive optic nerve T2 hyperintensity that is chiasm-sparing and with predominant anterior segment involvement on imaging." (PMID 35795797, 2022). "Plasma LCN2 levels were significantly higher in patients with MOG-IgG–positive optic neuritis than in controls and patients with MOG-IgG–negative optic neuritis." (PMID 35566760, 2022). "Among the 19 patients with optic neuritis, 6 demonstrated MOG-IgG seropositivity; the remaining 13 patients were diagnosed with MOG-IgG–negative optic neuritis." (PMID 35566760, 2022). "Myelin oligodendrocyte glycoprotein antibody associated disease (MOG-AD) is a CNS demyelinating disease, typically presenting with optic neuritis, transverse myelitis, and/or ADEM-like syndromes." (PMID 35795797, 2022). "Patients with CSF restricted MOG-IgG have similar clinical phenotype in comparison with seropositive ones, with the notable exception of isolated optic neuritis, which is uncommon in patients with CSF-restricted MOG-IgG." (PMID 35401423, 2022). "A retrospective case review found that documented treatments for MOG antibody-positive patients with acute attacks of optic neuritis and/or myelitis have included high-dose IV methylprednisolone (IVMP), plasma exchange, immunoadsorption, and oral steroids." (PMID 35399911, 2022). "The most common presenting symptom of MOG-AD is optic neuritis, followed by transverse myelitis like in our patient, and ADEM." (PMID 35399911, 2022). "Myelin oligodendrocyte glycoprotein (MOG) antibody disease most commonly presents with optic neuritis, though myelitis is also possible." (PMID 35399911, 2022). "Here, we present a case with anti-MOG positive bilateral optic neuritis and brainstem encephalitis secondary to COVID-19 infection." (PMID 36548183, 2022). "Discovery of a novel glial autoantibody specific for myelin oligodendrocyte glycoprotein (MOG) has enabled recognition of antigen-specific inflammatory demyelinating diseases of the central nervous system (CNS) manifesting as optic neuritis." (PMID 35566760, 2022). "This study aimed to evaluate the correlation between plasma lipocalin-2 (LCN2) levels and myelin oligodendrocyte glycoprotein (MOG)-immunoglobulin G (IgG) seropositivity in patients with optic neuritis." (PMID 35566760, 2022). "MOG-AD can result in recurrent attacks of myelitis or optic neuritis, and sometimes, patients are left with permanent deficits." (PMID 35399911, 2022). "Studies on experimental autoimmune optic neuritis (EAON) have shown that optic neuritis can be induced by adjuvant immunization with MOG peptides." (PMID 35566760, 2022). "In this study, we investigated the correlation between plasma LCN2 levels and MOG-IgG titers in patients with optic neuritis." (PMID 35566760, 2022).
optic neuritis (continued). "The purpose of this study was to measure plasma LCN2 levels and evaluate their correlation with MOG-IgG titers in patients with optic neuritis." (PMID 35566760, 2022). "Plasma LCN2 and MOG-IgG levels were significantly correlated in patients with optic neuritis (r = 0.553, p = 0.0141)." (PMID 35566760, 2022). "Recurrences of short duration between optic neuritis attacks occur more frequently in patients with MOG-IgG–positive optic neuritis than in those with MOG-IgG–negative optic neuritis." (PMID 35566760, 2022). "We found that patients with MOG-IgG–positive optic neuritis had significantly higher plasma LCN2 levels than healthy controls and patients with MOG-IgG–negative optic neuritis." (PMID 35566760, 2022). "There has also been a reported pediatric case of post-Lyme disease MOG antibody-positive short segment myelitis and optic neuritis." (PMID 35399911, 2022). "Myelin oligodendrocyte glycoprotein (MOG) antibody (MOG-Ab) disease (MOG-AD) is a type of demyelinating disease of the central nervous system characterized by a high frequency of optic neuritis (ON) attacks." (PMID 33429822, 2021). "Anti-MOG optic neuritis can present with recurrent symptoms of visual impairment and have a good response to steroids." (PMID 34484845, 2021). "Myelin oligodendrocyte glycoprotein (MOG) antibodies are associated with relapsing syndromes involving brainstem or cortical encephalitis, sometimes with optic neuritis and transverse myelitis, which particularly involve children and young adults." (PMID 34108243, 2021). "MOG-Ab disease (MOG-AD) is a type of demyelinating disease of the central nervous system characterized by a high frequency of optic neuritis (ON) attacks." (PMID 33429822, 2021). "Compared to anti-AQP4 antibody NMOSD, optic neuritis lesions in anti-MOG antibody NMOSD are relatively longer but less likely to reach optic chiasma and are confined in the anterior portion of the optic nerve in MRI." (PMID 34484845, 2021). "Recent studies have shown that MOG-ON has a more severe clinical presentation than classic optic neuritis (ON)." (PMID 32785840, 2021). "High rates of optic neuritis with immune cell infiltrations and demyelination were also observed in MOG-induced EAE mice." (PMID 34721390, 2021). "In approximately 1/3 cases of MOG-EM, there was optic neuritis with inflammation and enhancement of the perioptic nerve sheath, partly extending into the surrounding orbital fat." (PMID 34327021, 2021). "MOG-IgG-associated disease (MOGAD) is increasingly recognized as a distinct entity, characterized by optic neuritis, transverse myelitis and/or brain stem syndrome in combination with positive MOG-IgG." (PMID 33011853, 2021). "In recent studies, a new-generation cell-based assay (CBA) have demonstrated an association of MOG-IgG with inflammatory CNS demyelinating disorders, like acute demyelinating encephalomyelitis (ADEM), optic neuritis (ON) and myelitis." (PMID 33422038, 2021). "Even if some studies report functional and microstructural damages in MOG-Ab optic neuritis, visual recovery measured by visual acuity seems poorer in double seronegative and AQP4-Ab patients with optic neuritis." (PMID 32326965, 2020). "In a recent study, 110 MOG-IgG positive patients with optic neuritis were evaluated comparing clinical characteristics and outcome according to the age of presentation: pediatric, young (18–46 years) and middle-aged (>46 years) adult patients." (PMID 32671002, 2020). "In the early 1990s, more than 10 years before the serum AQP4-IgG and MOG-IgG were measured in patients with ON, a landmark clinical trial of the Optic Neuritis Treatment Trial (ONTT) was performed." (PMID 33013632, 2020). "In terms of clinical syndromes experienced at any point during the disease course, MOG-antibody positive patients were more likely to have experienced optic neuritis (74 vs. 40%) or brainstem (38 vs. 21%) presentations than the seronegative group." (PMID 33510701, 2020).
optic neuritis (continued). "Approximately 30% of these mice will develop spontaneous optic neuritis; when immunized with subclinical levels of MOG peptide, up to 56% developed histological evidence of EAE." (PMID 33224094, 2020). "Antibodies against MOG are found mostly in patients with optic neuritis (ON), acute disseminated encephalomyelitis (ADEM), and aquaporin-4 antibody (AQP4-abs)-seronegative neuromyelitis optica spectrum disorders (NMOSD)." (PMID 33584514, 2020). "These 47 patients had typical MOG-IgG-associated clinical phenotypes such as optic neuritis, ADEM, myelitis, AQP4-seronegative NMOSD, or other demyelinating phenotypes reported to be associated with MOG-IgG." (PMID 32024795, 2020). "A study from Germany examined different groups of MS patients for MOG antibodies and found a rate of 5% MOG-antibody positivity in a group selected for “NMOSD-type presentations” with severe optic neuritis, myelitis and brainstem presentations." (PMID 33510701, 2020). "Further analyses of the pVEPs and other clinical findings of the optic neuritis are needed to establish the clinical significance of the anti-MOG antibodies positivity and optic neuritis for the diagnosis, treatment, and prognosis for this disease." (PMID 31920953, 2019). "The clinical phenotypes of children with MOG-Ab-associated disease include monophasic ADEM, ADEM followed by recurrent optic neuritis (ON), or AQP4-negative NMOSD." (PMID 30671648, 2019). "Acute disseminated encephalomyelitis and bilateral or recurrent optic neuritis are the most frequent anti-MOG syndromes in children and adults, respectively." (PMID 31212763, 2019). "We describe the case of a 45-year-old man with MOG-IgG1-positive highly relapsing optic neuritis who had experienced 5 attacks over 21 months and had monocular blindness despite prednisolone and azathioprine therapy." (PMID 30577778, 2018). "In patients with MOG-Abs, optic neuritis was the first clinical manifestation in 33–64% whereas myelitis occurred in 18–33% of the patients as initial symptom." (PMID 30405519, 2018). "Optic neuritis is the most prominent disease manifestation in MOG-abspositive patients, who often present with simultaneous optic neuritis and myelitis at onset, with optic neuritis at relapse [32▪▪], and with bilateral simultaneous optic neuritis." (PMID 29465432, 2018). "At onset, patients with MOG-Abs are more likely to suffer from simultaneous or rapidly sequential optic neuritis and LETM compared to patients with AQP4-Abs." (PMID 30405519, 2018). "In NMOSD and MOG-EM, most common symptoms are optic neuritis and longitudinally extensive transverse myelitis (LETM)." (PMID 30405519, 2018). "We also assessed the proportion of patients with optic neuritis and long myelitis who fulfill Wingerchuk 2006 criteria that are MOG-IgG positive, as this is a clinical question often posed." (PMID 28840314, 2017). "Barkhof’s criteria for DIS were fulfilled in 15% of the cases that were positive MOG antibody and had a history of transverse myelitis and/or optic neuritis, and in 26.9% of the cases that were positive for the MOG antibody and had a history of brain lesions." (PMID 29064441, 2017). "A broader age distribution existed in the MOG-ON group, with optic neuritis diagnosed in children and the elderly similar to MOG-NMOSD." (PMID 29064441, 2017). "MOG-positive optic neuritis is a rare disease, making a large-scale study of OCT findings a challenge that is not easy to overcome." (PMID 28125740, 2017). "In both series, optic neuritis was the most common initial symptom in 60–64% of the patients in isolation and 70–74% in combination, reflecting the increased expression of MOG in the optic nerve compared to other CNS areas." (PMID 29064441, 2017). "Bilateral, simultaneous optic neuritis attacks are more common in patients with MOG-IgG than in those with AQP4-IgG or in seronegative ones." (PMID 26950113, 2016).